BRCA1 (BRCA1 DNA repair associated)
Diseases named in the same sentence as BRCA1 in open-access papers (continued):
Sharing a sentence is not in itself a finding about the gene and the disease.
breast cancer (continued). "About 25% of TNBC patients carry breast cancer susceptibility genes 1 and 2 (BRCA1 and BRCA2) mutations." (PMID 37719058, 2023). "Germline mutations in the breast cancer susceptibility genes, BRCA1 and BRCA2, are the most common causes of hereditary breast and ovarian cancer (HBOC) syndrome." (PMID 35778884, 2023). "The present study explored the prevalence and characteristics of breast cancers in Thai patients tested for germline BRCA1/2 mutations." (PMID 35778884, 2023). "Among breast cancer-mutant genes, the most common genes are Breast Cancer Susceptibility Gene 1 (BRCA1) and Breast Cancer Susceptibility Gene 2 (BRCA2) involved in DNA repair." (PMID 37476378, 2023). "Many other models of breast cancer have focused on one aspect or another of the development of the tumor, the influence of genetic predisposition (e.g., BRCA1&2 or the path to metastasis." (PMID 37205649, 2023). "Performing prophylactic mastectomy to reduce the risk of contralateral breast cancer and prophylactic ovariectomy are two types of surgery proposed to women with BRCA1 and BCRA2 gene abnormalities." (PMID 37055759, 2023). "In general, approximately 5-10% of breast cancers are hereditary, mostly due to pathogenic variants or mutations in the BRCA1 and BRCA2 genes." (PMID 38169859, 2023). "Collectively, genetic testing of BRCA1/2 mutations is recommended for HER-2-negative metastatic breast cancer patients to accurately screen the potential clinical benefit of PARP inhibitors." (PMID 38068930, 2023). "It has been reported that mutation of BRCA1 is closely related to the occurrence poor prognosis of breast cancer." (PMID 36906594, 2023). "Proportions vary with ancestry, but an estimated 5–10% of breast cancer cases carry germline variants in genes associated with moderate to strong breast cancer risk (e.g., BRCA1, BRCA2, and CHEK2)." (PMID 37060015, 2023). "Breast cancer-associated gene 1 (BRCA1) is a familiar tumor suppressor gene, and BRCA1 deficiency can contribute to various breast cancers." (PMID 37701037, 2023). "Of 288 patients who developed breast cancer after being enrolled in the study, 19 (6.6%) carried BRCA1 P/LP (n = 8) or BRCA2 P/LP (n = 11) germline variants." (PMID 37628558, 2023). "Talazoparib monotherapy was used in this trial to treat HER2-negative metastatic breast cancers with germline BRCA1/2 mutation." (PMID 37035242, 2023). "In SSA countries, only a few studies have explored hereditary BC through genetic analysis of breast cancer susceptibility genes such as BRCA1, BRCA2, and others." (PMID 35908255, 2023). "For breast cancer patients, the results of the TBCRC-048 and TBB trials suggested further exploration of PARP inhibitors in metastatic or advanced breast cancers with HR-associated mutations beyond BRCA1 and BRCA2." (PMID 38098088, 2023). "The majority of inherited breast cancers (5–10% of cases) are caused by mutations in the tumor-suppressor genes, breast cancer 1/2 (BRCA1/2)." (PMID 37893470, 2023). "The first evidence of breast cancer risk reduction with tamoxifen in healthy BRCA1 and BRCA2 germline variant carriers came from a subgroup analysis of the P-1 trial." (PMID 37628558, 2023). "Regarding breast cancer, most of the work looked at mutations in BRCA1 and BRCA2 with several studies reporting novel variants in these genes." (PMID 37662839, 2023). "In Poland approximately 4% of patients with breast cancers and 10% of patients with ovarian cancer carry a mutation in BRCA1." (PMID 37312208, 2023). "For example, CDDO-imidazolide induces G2/M cell cycle arrest in BRCA1-mutated breast cancer cells, while CDDO-Me significantly arrests cells in the G2/M and S phases in K562 cells." (PMID 37242425, 2023). "Inherited mutations in the breast cancer susceptibility genes BRCA1 and BRCA2 (BRCA1/2) confer high risks of breast and ovarian cancer." (PMID 37055759, 2023).
breast cancer (continued). "On the other hand, sex hormones are involved in the development of breast cancer associated with BRCA1 mutations." (PMID 37893470, 2023). "Breast cancers with BRCA1 mutation carriers are frequently categorized as triple-negative basal-like, and their prevalence rate is around 80%–90%." (PMID 36873936, 2023). "Pathogenic variants of breast cancer susceptibility genes 1 or 2 (BRCA1/BRCA2) reportedly occur in nearly 5% of patients with breast cancer." (PMID 36865806, 2023). "The increased risk of breast cancer at earlier ages leads to particular concern about preventive strategies in carriers of P/LP variants in BRCA1/2 genes." (PMID 36971799, 2023). "Carriers of germline pathogenic variants in the BRCA1 or BRCA2 breast cancer predisposition genes have high breast cancer risks." (PMID 37340476, 2023). "Current evidence suggests that carriers of BRCA1/2 pathogenic variants have similar clinical outcomes as sporadic breast cancer." (PMID 36980802, 2023). "Studies have found that co‐culture of CAF with the conditioned medium of BRCA1‐deficient human breast cancer cells HCC1937 can increase the expression level of ezrin mRNA in CAF by 30‐fold, which helps tumor cells to metastasize and invade." (PMID 37171030, 2023). "It has been demonstrated that breast cancers with BRCA1 mutations are more likely to be of high histological grade or triple-negative compared with tumors with a BRCA2 mutation." (PMID 37173992, 2023). "For patients with germline BRCA1/2 mutations with metastatic HER2-negative breast cancer, treatment with the PARPis olaparib or talazoparib is associated with more prolonged progression-free survival compared to regular chemotherapeutic treatments." (PMID 37195374, 2023). "This study aimed to conduct a network meta-analysis to assess the efficacy and safety of various pharmacotherapies for patients with metastatic, locally advanced, or recurrent breast cancer carrying BRCA1/BRCA2 pathogenic variants." (PMID 36865806, 2023). "BRCA1-associated breast cancers are known to frequently present with benign features, such as round shape, circumscribed margins, and a homogeneous internal structure." (PMID 36905492, 2023). "About 25% of TNBC patients carry germline breast cancer gene types 1 and 2 (BRCA1 and BRCA2) mutations." (PMID 37719058, 2023). "By the age of 70, individuals with BRCA1 mutations had an estimated breast cancer penetrance of 64.6% (95% CI = 59.5% to 69.4%), while those with BRCA2 mutations had a penetrance of 61.0% (95% CI = 48.1% to 72.5%)." (PMID 37781206, 2023). "We retrospectively reviewed all breast cancer patients who were tested for germline BRCA1/2 mutations during 2014–2018." (PMID 35778884, 2023). "Specifically, breast cancer tends to develop earlier in BRCA1 variant carriers, and their tumors are predominantly ER-negative." (PMID 38201529, 2023). "Further, a larger proportion of young women with breast cancer carry pathogenic variants in cancer predisposition genes such as BRCA1/2, compared to late-onset breast cancer." (PMID 36980802, 2023). "The U.S. Food and Drug Administration approved two PARP inhibitors, olaparib and talazoparib, as treatment options for patients with metastatic or advanced breast cancer carrying germline BRCA1/2 pathogenic variants." (PMID 36865806, 2023). "Protein-truncating variants in BRCA1 generally confer around 8 to 10-fold increased risk of breast cancer." (PMID 37790698, 2023). "Taken together, these findings indicate that around 20% of all TNBC/ER-low breast cancers and around 65% of all BRCA1-methylated tumors occur in individuals with underlying constitutional BRCA1 methylation." (PMID 38053165, 2023).
breast cancer (continued). "A systematic review of twenty-one observational studies in healthy BRCA1/2 carriers describes that a risk-reducing mastectomy effectively reduces both the incidence and mortality of breast cancer." (PMID 37372873, 2023). "The frequency of a variant of uncertain significance (VUS) of BRCA1/2 in breast cancer varies among different studies; a recent study reported a rate of 9% mostly in non-BRCA1- or BRCA2-carrying tumors." (PMID 37173992, 2023). "While realizing that only 45% of familial breast cancer cases were associated with BRCA1, the search for another breast-cancer-susceptibility gene emerged." (PMID 37509303, 2023). "BRCA1-associated cancers are breast, uterine and ovarian cancer in women, prostate and breast cancer in men, a moderately increased risk for pancreatic cancer in both and acute myeloid leukemia in children." (PMID 37626783, 2023). "Olaparib and talazoparib currently are the only PARPi approved for patients with hormone receptor-positive/HER2-negative advanced breast cancer and a BRCA1 or BRCA2 mutation detected by germline sequencing." (PMID 38414963, 2023). "Alleles within the cancer susceptibility locus chr19p13.1 were first found to modify the risk of breast cancer in BRCA1 mutation carriers, triple negative breast cancer (TNBC), and ovarian cancer." (PMID 36859531, 2023). "The early onset of breast cancer is common in females that harbor the mutations of BRCA1 with approximately 80% of them presenting with aggressive triple-negative tumors." (PMID 37623253, 2023). "The NCCN criteria for genetic testing includes any woman with breast cancer of Ashkenazi Jewish descent, due to the established frequency of pathogenic variants in BRCA1 and BRCA2 in this population." (PMID 36544278, 2023). "An ongoing phase III trial in postmenopausal women carrying BRCA1/2 mutations is underway to investigate breast cancer incidence and recurrence with letrozole therapy (LIBER trial; NCT00673335)." (PMID 37583424, 2023). "In breast cancer, some of the mutations are inherited breast cancer gene 1 and 2 (BRCA1, BRCA2), but most of them are acquired during the lifetime due to environment and lifestyle exposure or after chemotherapy." (PMID 36675137, 2023). "In this context, our study assessed breast cancer surveillance behaviors among a cohort of Sri Lankan women genetically predisposed to breast cancer with BRCA1 or BRCA2 pathogenic variants." (PMID 38017478, 2023). "Based on these findings, we suggest routine screening for variants in ARID1A along with BRCA1/2 in breast cancer patients from the Mexican-mestizo population." (PMID 37182128, 2023). "In patients carrying pathogenic variants, the BRCA1/2 genes show incomplete penetrance and the cumulative risk at the age of 80 years is up to 72% for breast cancer in BRCA1 P/LP variants carriers and up to 69% in BRCA2 P/LP variants carriers." (PMID 36971799, 2023). "Recently, it has been reported that 13% of high-risk Cypriot breast cancer patients are positive for PVs in BRCA1 and BRCA2." (PMID 37790698, 2023). "For cancer cell-derived inflammasomes, NLRP3 inflammasomes and downstream IL-1β secretion can be activated by breast cancer susceptibility gene 1 (BRCA1) deficiency through ROS production leading to promoted metastasis in breast cancer cells." (PMID 36932407, 2023). "BRCA1 and 2 mutations are known to be associated with breast cancer, and olaparib, a poly (adenosine diphosphate-ribose) polymerase (PARP) inhibitor, has been shown to be effective in cells carrying these mutations in some studies." (PMID 37692183, 2023). "For the prevention of breast cancer, risk-reducing bilateral mastectomy is an effective procedure to reduce breast cancer incidence for both BRCA1 and BRCA2 PV carriers and breast cancer mortality for BRCA1 PV carriers." (PMID 36767056, 2023).
breast cancer (continued). "Breast cancer susceptibility genes 1 and 2 (BRCA1 and BRCA2) are antioncogenes expressed in the breast and ovarian cells of women genetically predisposed to breast and ovarian cancer, where they play an important role in the repair of the chromosomal damage." (PMID 37112468, 2023). "For instance, BRCA1 promoter methylation or other potential mutations in DDR genes can lead to BRCA1/2 deficiency in patients with breast cancer." (PMID 37350936, 2023). "In early-onset breast cancer, concurrent germline variants of BRCA1, BRCA2, PMS2, and PALB2 were reported." (PMID 37628631, 2023). "Breast cancer genes 1 and 2 (BRCA1 and BRCA2) are tumor suppressor genes, and mutations in either strongly increase the risk of the carrier towards developing breast and ovarian cancer." (PMID 37108225, 2023). "Anthropometric measures are associated with breast cancer risk for BRCA1 and BRCA2 variant carriers, with relative risk estimates that are generally consistent with those for women from the general population." (PMID 37340476, 2023). "Germline BRCA1/2 carriers were associated with a younger age at diagnosis, greater Ki67 index values, higher frequencies of bilateral breast cancer, positive lymph node status, and a family history of breast or ovarian cancer (FBOC)." (PMID 38114467, 2023). "In BRCA1 carriers, breast cancer (72.5%) ranked first by the cumulative risk, followed by ovarian cancer at 65.6% and gastric cancer at 21.3%." (PMID 37476378, 2023). "To investigate and compare the contribution of CAFs to the TME of different breast cancer subtypes we used our established GEMMs that closely mimic human breast cancer histology of BRCA1-deficient TNBC and E-cadherin-deficient ILC." (PMID 36635273, 2023). "In another study, researchers reviewed 114 NSM performed from 2008 to 2019 on patients with breast cancer in 105 BRCA1/2 carriers (56 BRCA1, 47 BRCA2, and two women with both mutations)." (PMID 37781190, 2023). "This high prevalence of LOH for BRCA1/2mut is consistent with previous studies in breast cancer where loss of the wildtype chromosome was seen in 88–89% of BRCA1/2mut patients." (PMID 37803017, 2023). "This complex, identified as discrete foci within the nucleus, was dramatically reduced in HCC/1937 breast cancer cells bearing a homozygous BRCA1 mutation yet was restored via wild-type BRCA1 transfection." (PMID 37762577, 2023). "The common ALDH2 variant rs671 severely aggravates DNA repair‐deficient disorder Fanconi anemia, and it is expected that breast cancer developed in BRCA1/2 mutation carriers are similarly affected." (PMID 36345163, 2023). "Among PDXs from patients with germline BRCA1/2-mutated breast cancer, 2 of 9 PARPi-resistant models had somatic mutations in TP53BP1 and exposure to olaparib in PDX models correlated with reduced mRNA expression of SHLD1 and SHLD2." (PMID 37430137, 2023). "Supporting a role for BRCA1/2 in GBC, the Breast Cancer linkage consortium studied coincident cancers among 681 individuals with breast or ovarian cancer and 3047 carriers of BRCA1 or BRCA2 variants." (PMID 38163482, 2023). "Based on these findings, a loss of PTEN, which is highly associated with BRCA1-mutated breast cancer, appears to promote PARPi-sensitivity." (PMID 37509303, 2023). "Circulating cell-free nucleic acids biomarkers such as microRNAs (miRNAs) and breast cancer susceptibility gene 1 (BRCA1) allow the characterization of the genetic features and screening breast cancer patients." (PMID 37112468, 2023). "Female BRCA1/2 PV carriers face a lifetime risk of roughly 70% for breast cancer (BRCA1: 95% confidence interval (CI) 65–79; BRCA2 95% CI 61–77)." (PMID 36767056, 2023).
breast cancer (continued). "Our study presents the one of the largest cohorts of breast cancer patients with BRCA1, BRCA2, and PALB2 mutations detected through tumor-only sequencing in Taiwan." (PMID 38098088, 2023). "We aimed to assess the prevalence and characteristics of Thai patients with breast cancer with germline BRCA1/2 mutations." (PMID 35778884, 2023). "As data on the prevalence of BRCA1/2 mutations matured, it became evident that pathogenic variants (PVs) in these genes accounted for less than two-thirds of hereditary breast cancer, leading to a search for additional breast cancer predisposition genes." (PMID 37084156, 2023). "Among the four FDA-approved PARP inhibitors, Olaparib and Talazoparib are currently being used for the treatment of breast cancer patients with BRCA1/2 deficiencies." (PMID 38201253, 2023). "BARD1 (BRCA1-associated RING domain 1) is an essential gene related to breast cancer development that encodes a protein that interacts with the N-terminal region of BRCA1." (PMID 36765720, 2023). "By the age of 80, BRCA1/2 mutation carriers have a 70% risk of developing breast cancer, which is seven times higher than the general population (10%)." (PMID 37987348, 2023). "OLA, a potent cytotoxic anticancer drug, is administrated for the treatment of patients with advanced, recurrent ovarian cancer who have mutations of breast cancer BRCA1 or breast cancer BRCA2." (PMID 37376117, 2023). "One of the most well-known and widespread is the BRCA1 c.5266dupC germline mutation in exon 20, which is associated with a high risk of breast cancer and ovarian cancer." (PMID 37628606, 2023). "Using chromatin immunoprecipitation (ChIP) assay, Johnston and colleagues demonstrated that BRCA1 associates with the rDNA loci in multiple breast cancer cell lines." (PMID 37035242, 2023). "Nearly 20% of patients with TNBC harbor a breast cancer susceptibility gene (BRCA) mutation, particularly BRCA1, compared to 6% of all breast cancers associated with a BRCA mutation." (PMID 37569851, 2023). "It has also been observed that BRCA1 mutations are highly prevalent among Qatari patients with breast cancer due to tribal founder effects that can partially explain the frequent young-onset diagnosis of breast cancer in the State of Qatar." (PMID 37335020, 2023). "Genetic mutations have been reported to associate with ovarian cancer progression, such as BRCA1 (breast cancer 1) mutation and BRCA2 (breast cancer 2) mutation." (PMID 38152652, 2023). "In consequence, BRCA1-mutated breast cancer cells harbor significantly higher insertion-deletion mutations around known transcription termination sites, suggesting that BRCA1-directed resolution of R-loops halts tumorigenesis." (PMID 37108225, 2023). "Pathogenic and Likely Pathogenic (P/LP) genetic variants in the BRCA1/2 (Breast Cancer 1/2) genes are the main cause of hereditary breast cancer." (PMID 36845387, 2023). "Data on the efficacy of tamoxifen, raloxifene, and aromatase inhibitors on breast cancer primary prevention in women carrying BRCA1 or BRCA1 and BRCA2 P/LP germline variants are scarce." (PMID 37628558, 2023). "An estimated 5–10% of breast cancers are linked to hereditary mutations, most commonly within the BRCA1 or 2 loci, which increases lifetime risk as high as 60–85% 6–8." (PMID 37961240, 2023). "The EMBRACA phase 3 trial showed that the single-agent talazoparib significantly benefited patients with advanced breast cancer and a germline BRCA1/2 mutation over standard chemotherapy." (PMID 37173992, 2023). "Recently, 21 candidate genes, including BRCA1 and 2, were associated with breast cancer risk in a large case–control study." (PMID 36409394, 2023).